FCGR2B (Fc gamma receptor IIb)
Diseases named in the same sentence as FCGR2B in open-access papers (continued):
Sharing a sentence is not in itself a finding about the gene and the disease.
metastatic disease (2 papers, 2022 to 2024). "Intriguingly, FCGR2B (FcγRIIB) mRNA expression levels were especially increased in iliopsoas muscle and liver metastatic tumors, potentially emphasizing the role of M2 macrophages in the pathogenic mechanism of HPD." (PMID 39289546, 2024).
multiple myeloma (2 papers, 2015 to 2025). "Importantly, elevated Fcgr2b expression has been observed on CD8+ tumor‐infiltrating lymphocytes in patients with myeloma and in patients with SARS‐CoV‐2." (PMID 41116748, 2025).
parasitemia (2 papers, 2014 to 2023). "In this study, we observed that the CC-genotype at position rs1050501 in the FCGR2B gene was associated with enhanced parasitemia in adults." (PMID 37958695, 2023).
periodontal disease (2 papers, 2021 to 2022). "As shown in the boxplot, the expression of CD14, FCGR1A, DYNLL1, and FCGR2B correlated with disease status; therefore, these data suggest that these key genes may be important targets for the treatment of periodontal disease." (PMID 36212719, 2022).
sarcoidosis (2 papers, 2017 to 2023). Sarcoidosis is a multisystemic disorder of unknown cause characterized by the formation of immune granulomas in involved organs. "Therefore, we have analyzed polymorphism of these genes in our SA patients and revealed that, in contrast to polymorphism of FCGR2B and FCGR3B, polymorphism of FCGR2A, FCGR2C and FCGR3A may contribute to immunocomplexemia present in sarcoidosis." (PMID 28472129, 2017). "We have found a lack of association between copy number of FCGR2A, FCGR2B, FCGR2C, FCGR3A, FCGR3B genes and risk of development of sarcoidosis in our patients." (PMID 28472129, 2017).
central nervous system infection (1 paper, 2012). "We found for the first time associations between cryptococcal meningitis and FCGR2B 232I/T genotypes, which suggested that FcγRIIB might play an important role in the central nervous system infection by Cryptococcus in HIV-uninfected individuals." (PMID 22879986, 2012).
Cerebral ischemia (1 paper, 2022). Restriction of arterial blood supply to the brain associated with insufficient oxygenation to support the metabolic requirements of the tissue. "The results of a mouse experimental model with cerebral ischemia showed that the expression level of Fcgr2b of microglia/macrophage activated by inflammatory reaction remained unchanged." (PMID 36030234, 2022).
Cryptococcal meningitis (1 paper, 2012). Meningeal inflammation produced by cryptococcus neoformans, an encapsulated yeast that tends to infect individuals with acquired immunodeficiency syndrome and other immunocompromised states. "Similar to results from the overall patient group, associations were also found between FCGR2B 232I/T genotypes and cryptococcal meningitis based on dominant and over-dominant model." (PMID 22879986, 2012). "Distribution of FCGR2A, FCGR3A, FCGR3B, FCGR2B genotypes in patients with cryptococcal meningitis and controlsa." (PMID 22879986, 2012). "In our study, we found for the first time that cryptococcal meningitis was associated with the FCGR2B 232I/T genotypes, which was not reported in Metediatis’ study." (PMID 22879986, 2012). "In this case control genetic association study, we genotyped four functional polymorphisms in low-affinity FcγRs, including FCGR2A 131H/R, FCGR3A 158F/V, FCGR3B NA1/NA2, and FCGR2B 232I/T, in 117 patients with cryptococcal meningitis and 190 healthy controls by multiplex SNaPshot technology." (PMID 22879986, 2012). "In cryptococcal meningitis patients without predisposing factors, FCGR2B 232I/I genotype was also more frequently detected (OR = 1.958, 95% CI [1.05–3.66]; P = 0.033), and the FCGR2B 232I/T genotype was also less frequently detected (OR = 0.467, 95% CI [0.24–0.91]; P = 0.023) than in controls." (PMID 22879986, 2012).
glomerulosclerosis (1 paper, 2024). A hardening of the kidney glomerulus caused by scarring of the blood vessels. "Next, the histological findings of the kidneys by H&E staining showed that Fcgr2b−/− mice developed fibrocellular crescent, glomerulosclerosis, and interstitial infiltration, while the treated Fcgr2b−/− mice with ISD017 and CYC had less severe disease (top row)." (PMID 38745067, 2024).
gout (1 paper, 2024). A condition characterized by painful swelling of the joints, which is caused by deposition of urate crystals. "In the druggability assessment, SLC7A7 and FCGR2B were validated, and both were significantly associated with relevant targets of the currently commercially available gout drugs Probenecid and Rilonacept, respectively." (PMID 39734218, 2024). "Ultimately, eight genes were identified as possible drug targets in gout, including three risk genes (ALDH3B1, NRBP1, SUMF1) and three protective genes (FCGR2B, RCE1, SLC7A7)." (PMID 39734218, 2024). "Eight potential therapeutic targets (ALDH3B1, FCGR2B, IL2RB, NRBP1, RCE1, SLC7A7, SUMF1, THBS3) for gout were identified in the discovery cohort using MR analysis." (PMID 39734218, 2024).
Hyperglycemia (1 paper, 2020). An increased concentration of glucose in the blood. "QPCR was performed to measure FCGR2B expression in whole blood samples of AA- first-degree relatives of T1D patients (AA- FDRs; n=15), AA+ FDRs who later progressed to hyperglycemia (AA+ progressors, n=20), and established T1D patients." (PMID 33424774, 2020).
hyperthyroidism (1 paper, 2020). Overactivity of the thyroid gland resulting in overproduction of thyroid hormone and increased metabolic rate. "The top five hub genes associated with hypothyroidism are ALB, MAPK1, SPP1, PPARG, and MIF, whereas those associated with hyperthyroidism are ALB, FCGR2B, CD44, LCN2, and CD74." (PMID 32500465, 2020). "After PPI network construction, the top five hub genes associated with hypothyroidism were extracted, including ALB, MAPK1, SPP1, PPARG, and MIF, whereas those associated with hyperthyroidism were ALB, FCGR2B, CD44, LCN2, and CD74." (PMID 32500465, 2020).
hypothyroidism (1 paper, 2020). Abnormally low levels of thyroid hormone. "A previous study indicated that the hypothyroidism due to rabbit immunoglobulins injection was attenuated in mice lacking FCGR3, but not in mice lacking FCGR2B." (PMID 32500465, 2020).
interstitial lung disease (1 paper, 2024). A diverse group of lung diseases that affect the lung parenchyma. "Significantly, a deficiency in Fcgr2b intensifies fibrosis, inflammation, and lung dysfunction in mice subjected to silica exposure, suggesting that Fcgr2b serves as a protective factor against progressive fibrosing interstitial lung disease." (PMID 38649840, 2024).
ischemia reperfusion injury (1 paper, 2022). Adverse functional, metabolic, or structural changes in ischemic tissues resulting from the restoration of blood flow to the tissue (reperfusion), including swelling; hemorrhage; necrosis; and damage from free radicals. "Thus, Emr1, Tyrobp, and Fcgr2b are fascinating therapeutic targets, the inhibition of which may protect the myocardium from ischemia-reperfusion injury." (PMID 35463067, 2022).
kidney failure (1 paper, 2017). An acute or chronic condition that is characterized by the inability of the kidneys to adequately filter the blood. "Eight genes related to kidney toxicity, including kidney failure (CASP1, FCGR2A, FCGR2B, TLR2, TLR4, P = 0.003), damage of renal tubule (TLR2, TLR4, P = 0.01), proximal tubular toxicity (CTSS, LYZ, SLC22A5, P = 0.007) and their expression across 6 datasets were not confounded by tissue types." (PMID 28051114, 2017).
lung fibrosis (1 paper, 2023). "According to the literature, two of them, Fcgr2b and Capg, might be more promising than the others since they have been identified in other studies on lung fibrosis with rat models or human patients." (PMID 37446067, 2023).
lymphoid tumor (1 paper, 2016). "Experimental models have demonstrated the potential of FCGR2B to promote tumorigenesis when expressed on non-lymphoid tumor cells." (PMID 27533245, 2016).
malignant glioma (1 paper, 2022). A grade III or grade IV glioma arising from the central nervous system. "Additionally, the expression of FCGR2B was highest in malignant gliomas (IDH_WT and BrMs) in MDMs." (PMID 36685974, 2022).
ovarian carcinoma (1 paper, 2023). A malignant neoplasm originating from the surface ovarian epithelium. "Accordingly, the other four genes, namely FCGR2B, CD53, CCR1, and SLAMF8, were previously identified as integral components of a larger tumor associated macrophage-related signature with prognostic potential in patients with ovarian cancer." (PMID 37509358, 2023).
prostate carcinoma (1 paper, 2022). A carcinoma that arises from epithelial cells of the prostate gland. "In this study, we performed next-generation sequencing-based gene expression analysis in peripheral blood from prostate cancer patients obtained pre- and post-radiotherapy and found six independently down-regulated genes including CCR7, FCGR2B, BTLA, CD6, CD3D, and CD3E." (PMID 36291815, 2022). "In this study, we performed gene expression analysis on peripheral blood from prostate cancer patients obtained post- radiotherapy and showed that 6 genes, including CCR7, FCGR2B, BTLA, CD6, CD3D, and CD3E, were down-regulated by a range of 1.5–2.5-fold as compared to pre-radiotherapy samples." (PMID 36291815, 2022).
pulmonary edema (1 paper, 2024). Accumulation of fluid in the lung tissues causing disturbance of the gas exchange that may lead to respiratory failure. "AAV-sh-Elk1 treatment upregulated the PaO2/FiO2 ratio and alleviated pulmonary edema, whereas AAV-sh-Elk1 and AAV-sh-Fcgr2b treatments diminished the PaO2/FiO2 ratio and exacerbated pulmonary edema." (PMID 38649840, 2024).
thrombotic microangiopathy (1 paper, 2025). The syndromes of microangiopathic hemolytic anemia, thrombocytopenia, and variable signs of organ impairment, due to platelet aggregation in the microcirculation. "Histological analysis of the rejected kidneys from B6.Fcgr2b KO mice showed thrombotic microangiopathy, glomerulitis and capillaritis, and transplant glomerulopathy, features characteristic of acute and chronic antibody mediated rejection (AbMR)." (PMID 40894037, 2025).
tumor (101 papers, 2010 to 2026). "Within the macrophages, we identified two clusters of tumor-associated macrophages (TAMs; Fcgr2b+, Ccl4+, Trem2+) and one enriched in complement genes (C4b+, Cfp+, C1qb+)." (PMID 38570533, 2024). "Genetic deficiency of Fcgr2b resulted in enhanced tumor-infiltrating CD8+ T cell responses and significantly reduced tumor burden." (PMID 33616086, 2021). "Furthermore, in a single-cell RNA-Seq (scRNA-Seq) analysis, we observed that FCGR2B is mainly expressed in tumor-associated macrophages (TAMs) and dendritic cells (DCs) and is preferentially expressed in recurrent GBM." (PMID 36685974, 2022). "Furthermore, scRNA-Seq analyses revealed that tumor-associated macrophage- and dendritic cell-specific FCGR2B was expressed." (PMID 36685974, 2022). "In the other single-cell RNA-seq analysis using the Brain Immune Atlas, we found that FCGR2B was almost expressed in tumor-associated macrophages (TAMs) and dendritic cells (DCs) and was expressed at higher levels in recurrent GBM samples than in newly diagnosed samples." (PMID 36685974, 2022). "Tumor cell-derived GM-CSF promotes Sp1 binding to the FCGR2B promoter to increase the expression of FcγRIIB that subsequently activates the Stat3 signaling pathway to promote generation of gMDSCs in the TME." (PMID 34976216, 2022). "FCGR2B expressed by myeloid effector cells inhibits direct tumor cell depletion by therapeutic antibodies via competition with its activating FCGR counterparts." (PMID 36291815, 2022). "Adoptive transfer experiments of Fcgr2b–/– tumor antigen-specific T cells into FcγRIIB-sufficient hosts resulted in an increased frequency of tumor-infiltrating CD8+ T cells with greater effector function." (PMID 33616086, 2021). "Results revealed a significant decrease in tumor volume in Fcgr2b–/– animals compared with WT controls." (PMID 33616086, 2021). "Statistically significantly increased numbers of Thy1.1+/Thy1.2+ Fcgr2b–/– OT-I T cells were identified in the spleens of coadoptive transfer hosts on day 14 after tumor inoculation compared with Thy1.2+ WT OT-I T cells." (PMID 33616086, 2021). "We observed similar phenotype that the anti-tumor activity of LOB12.3-mIgG1 is significantly reduced in Fcgr2b−/−, while 3H3-mIgG1 showed a weak but significant anti-tumor activity in Fcgr2b−/− mice." (PMID 31105267, 2019). "Consistent with its strong co-stimulation activity in vitro, 3H3-rIgG2a showed anti-tumor activity in both Fcgr2b−/− and Fcgr3−/− mice." (PMID 31105267, 2019). "However, WT OT-I were preferentially increased at the tumor compared with Fcgr2b–/– OT-I in Fgl2–/– hosts compared with WT hosts." (PMID 40125553, 2025). "Additionally, these antibodies can boost the immune system’s ability to fight tumors by blocking inhibitory signals from receptors like Fc gamma receptor IIB (FcγRIIB), enhancing their effectiveness in tumor therapy." (PMID 39335671, 2024). "Equally, tumor- or therapeutically-triggered hypoxia in the tumor microenvironment (TME) may increase FCGR2B expression on mononuclear cells and macrophages, thus hindering their ability to phagocytose tumor cells." (PMID 37509358, 2023). "Fcgr2b–/– mice have improved antitumor immunity and reduced tumor volume compared with WT mice." (PMID 33616086, 2021). "Furthermore, analysis of the tumor-infiltrating lymphocytes on day 14 revealed that Fcgr2b–/– CD8+ CD45.2+ OT-I T cells were present at significantly increased frequencies within the tumor relative to WT OT-I control cells." (PMID 33616086, 2021). "FCGR2B expression is thought to be a mechanism of immune escape by tumor cells." (PMID 27533245, 2016). "Additionally, rendering T cells insensitive to Fgl2 binding through FcγRIIB by engineering Fcgr2b–/– tumor-infiltrating lymphocyte or CAR-T therapies may preserve high-quality T cells important to the antitumor response." (PMID 40125553, 2025).
tumor (continued). "Among the receptors implicated in MDSC regulation, FC gamma receptor IIB (FCγRIIB/CD32B) is the sole inhibitory member expressed on B-cells, macrophages, dendritic cells (DCs) and granulocytes, with an upregulation of its expression observed in tumor-infiltrating MDSCs." (PMID 38983795, 2024). "However, in our analysis, neither tumor mutational burden (TMB) nor microsatellite instability (MSI) showed a significant relationship with mRNA expression of FCGR2B in the GBM database from TCGA." (PMID 36685974, 2022). "Examination of tumor-infiltrating immune cells revealed that SIGLEC10 and FCGR2B are frequently and highly expressed within the B cell cluster." (PMID 40894037, 2025). "We identified amplifications in oncogenes, including FCGR2B and CCND1, and deletions of tumor suppressors, such as CCNC and RB1, only in HPV-negative tumors." (PMID 37461056, 2023). "When the authors genetically eliminated the FCGR2B, tumor-infiltrating effector CD8+ T cell response was increased and the tumor was decreased." (PMID 36685974, 2022). "The expression levels of FCGR2B, IL10RA, and HLA-DRA in tumor samples (n=177) were significantly higher (q value < 0.001; log2FoldChange > 1) than in normal pancreatic tissue (n=171; from GTEx database)." (PMID 33845841, 2021). "Taken together, these data support the conclusion that regulation of FcγRIIB-competent tumor-specific CD8+ T cells, but not Fcgr2b–/– CD8+ T cells, are uniquely regulated via Fgl2." (PMID 40125553, 2025). "FC gamma receptor IIB (FCGR2B) overexpression in hematopoietic progenitor cells triggers the generation and expansion of myeloid-derived suppressor cells (MDSC) that target cytotoxic CD8+ T cells, thus hampering the intrinsic anti-tumor immune response." (PMID 37509358, 2023). "Importantly, although IFN-γ production was undetectable in WT tumor-infiltrating CD8+ T cells, Fcgr2b–/– T cells contained a high frequency (approximately 7%) of IFN-γ–producing effector CD8+ T cells on day 10 after tumor inoculation." (PMID 33616086, 2021). "In contrast to in vitro observations, anti-tumor efficacy of LOB12.3-rIgG1 was significantly impaired in Fcgr2b−/− but not Fcgr3−/− mice." (PMID 31105267, 2019). "Macrophage-secreted Fgl2 induces apoptosis of WT but not Fcgr2b–/– tumor-specific CD8+T cells." (PMID 40125553, 2025). "Fgl2 selectively regulates WT but not Fcgr2b–/– tumor-specific CD8+ T cells in vivo." (PMID 40125553, 2025). "Lastly, we sought to determine whether Fgl2 secreted by CD11b+ isolated from tumor-challenged mice was sufficient to induce apoptosis of FcγRIIB-competent but not Fcgr2b–/– OVA-specific CD8+ T cells." (PMID 40125553, 2025). "Moreover, FCGR2B, HLA-DQA2, and LTF are involved in tumor or organ transplantation." (PMID 35755170, 2022). "Previously, FCGR2B was believed to be expressed exclusively on B cells and innate immune cells, but recent studies have demonstrated a significant upregulation of FCGR2B on tumor-infiltrating effector CD8+ T cells, suggesting that it may serve as a novel T cell checkpoint in anti-tumor immunity." (PMID 38280005, 2024). "The six critical genes, including CCR7, FCGR2B, BTLA, CD6, CD3D and CD3E, play important roles in favoring tumor progression and promoting negative immune-regulatory effects." (PMID 36291815, 2022). "After coculture of CD11b+ cells isolated from a tumor-challenged mice with OVA-specific CD8+ T cells, FcγRIIB-competent CD8+ T cells were selectively driven to apoptosis by WT but not Fgl2–/– CD11b+ cells, a phenomenon that we did not observe in Fcgr2b–/– OVA-specific CD8+ T cells." (PMID 40125553, 2025).
cancer (48 papers, 2010 to 2026). A tumor composed of atypical neoplastic, often pleomorphic cells that invade other tissues. "qRT-PCR results revealed upregulation of SPHK1 and FPR2 in cancer tissues, whereas FCGR2B and VSIG4 were downregulated." (PMID 41150752, 2025). "The qRT-PCR data revealed significantly higher expression levels of SPHK1 (p < 0.01) and FPR2 (p < 0.05) mRNAs in CRC tissues compared to normal tissues, whereas the expression levels of FCGR2B mRNA were obviously lower in cancer tissues (p < 0.01)." (PMID 41150752, 2025). "There is also uncertainty regarding the influence of FCGR2A H131R and FCGR2B T232 in anti-cancer therapy." (PMID 37652365, 2023). "We further analyzed the correlation between the transcripts of FCGR2B and the HR of patient survival across cancers using univariate analysis." (PMID 36685974, 2022). "Of the ‘Cancer census genes’ most frequently involved in a copy number gain, four were in common with those in the TCGA-data (i.e. FCGR2B, TERT, CD79B and PRKAR1A)." (PMID 29371938, 2017). "A total of 5 genes were annotated for both cancer and inflammation: Fcgr2b, Egfr, Tnfaip3, Fas and Myd88." (PMID 27566565, 2016). "At present, the role of FCGR2B in CRC remains unclear, but it has been implicated in the progression and phagocytosis of several other cancers." (PMID 41150752, 2025). "Moreover, four cancer-associated genes showed a high frequency of copy number gain in both datasets (i.e. TERT, FCGR2B, CD79B and PRKAR1A)." (PMID 29371938, 2017). "The results showed that FCGR2B and VSIG4 expression in macrophages was upregulated in cancer samples, while FPR2 expression was downregulated." (PMID 41150752, 2025). "Research has elucidated that FCGR2B expression on mononuclear phagocytes is upregulated within the hypoxic TME, leading to a compromised phagocytic capability of these cells against cancer cells targeted by therapeutic antibodies." (PMID 40681545, 2025). "Through further analysis, we found that TYROBP, FCGR2B, TYROBP, LY86, and TLR2 genes were highly expressed in ccRCC carcinoma tissues." (PMID 36595751, 2022). "Moreover, both sample sets shared four genes in their ‘top 20’ list of ‘Cancer census genes’ most frequently involved in a copy number gain (i.e. TERT, FCGR2B, CD79B and PRKAR1A)." (PMID 29371938, 2017).